IL6 (interleukin 6)
Diseases named in the same sentence as IL6 in open-access papers (continued):
Sharing a sentence is not in itself a finding about the gene and the disease.
central nervous system disorder (10 papers, 2017 to 2024). A disease involving the central nervous system. "In addition, it associated these genes with the research articles on disorders of the central nervous system during chronic IL-6 overexpression at p < 0.00001 and with articles on stress-caused transcriptome changes at p < 0.001, among other research papers." (PMID 31921305, 2019). "Regarding IL-6, its high expression can accelerate the pathological processes of central nervous system disorders." (PMID 28923114, 2017). "It is involved in astrocyte activation, generation of pro-inflammatory factors IL-6, IL-1β, and TNF-α, and macrophage and T-cell infiltration, thus leading to secondary inflammatory injury in central nervous system diseases." (PMID 31681297, 2019).
hematological cancers (10 papers, 2016 to 2025). "We found that factors known to promote bone loss in solid and hematologic cancers (IL-6, MCP-1 and IL-3) were significantly elevated serum from Gzmb-HBZ mice compared to WT mice, indicating HBZ-mediated changes in cytokine secretion may directly or indirectly accelerate bone loss in this model." (PMID 29050201, 2017). "In direct mechanisms, gut microbes enter the bloodstream and activate IL-6 signals of the host to promote hematological tumor progression." (PMID 37190210, 2023). "While CXCL8 and IL-6 were the most important factors that segregated Severe-Death solid tumors patients, CXCL8, CRP and IL-6 had important roles for segregation of patients with hematologic cancers." (PMID 36700209, 2022). "Several inflammatory cytokines, including tumor necrosis factor-α (TNF-α), interferon-γ, interleukin (IL)-6, and IL-8, play a role in the pathogenesis of both immune-mediated diseases and hematologic cancers." (PMID 29287101, 2017). "In early studies, monoclonal anti-IL-6 antibodies (Abs) were reported to improve clinical and biological symptoms of PIS in patients with solid and hematological tumors." (PMID 39754984, 2025).
endocrinopathy (9 papers, 2012 to 2025). "Among patients presenting with elevated IL-6, endocrinopathy, higher free light chains, lower serum albumin, ascites, hepatomegaly and abnormal DLCO were all more common." (PMID 40646134, 2025). "IL-6 has also been involved in metabolism, endocrine, and neoplastic disorders, and the endocrinopathy is also a motivator of autoimmune." (PMID 23049597, 2012). "Nine studies examined changes in IL-6 by using various probiotics in different endocrine disorders." (PMID 38504163, 2024). "It seems that regulating the immune system and suppressing pro-inflammatory pathways like tumor necrosis factor-α and interleukin-6 or triggering anti-inflammatory pathways like interleukin-4 and 10 may be one of the potential mechanisms in the managing of endocrine disorders." (PMID 38504163, 2024).
blood cancer (8 papers, 2016 to 2025). "We observed that STING was positively correlated with IFN-γ and IL6/JAK/STAT3 signaling in most blood cancers." (PMID 39975558, 2025). "Similarly, in this study we report that secretion of MMP9 and IL-6 were significantly increased from monocytes upon stimulation with EVs from several blood cancer cell lines." (PMID 33984826, 2021). "Results from this study so far demonstrate that blood cancer-derived EVs significantly enhance MMP9 and IL-6 secretion from monocytes, which is attenuated by deletion of CypA." (PMID 33984826, 2021). "To date, the effect of blood cancer EVs on MMP-9 and IL-6 secretion remains unknown." (PMID 33984826, 2021). "CypA-enriched blood cancer EVs were taken up by normal monocytes independent of EV surface trypsin-sensitive proteins and potently stimulated pro-inflammatory MMP9 and IL-6 secretion." (PMID 33984826, 2021).
colon (7 papers, 2017 to 2023). "Interleukin-6 (IL-6) regulates multiple pro-malignant functions of CAFs in digestive system cancers by binding the IL-6R and activating the JAK kinase and the downstream pathway." (PMID 35327514, 2022).
bone disorder (5 papers, 2016 to 2024). "IL-6 stimulates osteoclast formation and promotes bone resorption in conditions like estrogen deficiency and in severe skeletal diseases." (PMID 39449745, 2024). "The association between inflammatory cytokines and bone disorders markers, IL-6, TNF-α, OPN, OPG, and FGF-23, reflects the severity of vascular changes in CKD and predicts disease progression." (PMID 27667892, 2016). "Out of all analyzed candidate biomarkers, a panel which includes mediators of inflammation (IL-6, TNF-α) and mineral and bone disorder biomarkers (OPG, OPN, OCN, FGF-23, and Fetuin-A) was found to be more relevant than a single biomarker to detect patients in early CKD stages." (PMID 27667892, 2016). "A panel of proteomic biomarkers, assessed by xMAP array, which includes mediators of inflammation (IL-6, TNF-α) and mineral and bone disorder biomarkers (OPG, OPN, OCN, FGF-23, and Fetuin-A), was found to be more relevant than a single biomarker to detect early CKD stages." (PMID 27667892, 2016).
genetic disease (5 papers, 2016 to 2025). "In addition to these genetic disorders, the production of inflammatory cytokines, such as interleukin-6 (IL-6) and matrix metalloproteinases (MMPs), which lead to extracellular matrix degradation resulting in fragility of the vascular wall, have been implicated in the development of AD." (PMID 35008739, 2021).
neoplastic disorders (5 papers, 2012 to 2021). "Interleukin 6 (IL-6) is an inflammatory cytokine involved in both metabolic and neoplastic disorders." (PMID 34681797, 2021). "With increasing insight into the complex signaling events induced by IL-6, more specific blockade of the anti-inflammatory functions of IL-6 has been developed to treat autoimmune and neoplastic disorders." (PMID 31632401, 2019). "During the last 15 years the pleiotropic effects of IL-6 in different organ systems have been reveled, and anti-IL-6 treatment has been approved for autoimmune and neoplastic disorders." (PMID 28642760, 2017). "An advantage of anti-IL6 or anti-IL6-receptor therapy is the knowledge gained from previous clinical trials for the treatment of rheumatologic and neoplastic disorders." (PMID 25738292, 2015).
gynecological diseases (3 papers, 2019 to 2023). "A multiple-array SPRi biosensor has been developed for the simultaneous determination of CA125, HE4, CEA, IL-6 and aromatase, which are useful in the diagnostics of oncological and gynecological diseases." (PMID 36832045, 2023). "The aim of this work was to develop a multiple biosensor for the simultaneous determination of five biomarkers: CA125, HE4, CEA, IL-6 and aromatase, which are useful in the diagnostics of oncological and gynecological diseases." (PMID 36832045, 2023).
gynecological tumors (2 papers, 2019 to 2024). "Little data are available on serum IL-6 in gynecological tumors, especially on CC." (PMID 38541074, 2024).
movement disorder (2 papers, 2012 to 2017). Neurological conditions resulting in abnormal voluntary or involuntary movement, which may impact the speed, fluency, quality and ease of movement. "Also within the group of movement disorders, the specificity of IL-6 elevations has been questioned." (PMID 23082161, 2012).
electrolyte imbalance (1 paper, 2020). "Results showed that seven parameters, the NLR, PLR, IL‐6, CRP, CT score, patients who need nutrition support, and electrolyte imbalance, were positively correlated with the risk of critical patients." (PMID 32860454, 2020).
mitochondrial disease (1 paper, 2020). "FGF21, GDF15, as well as VEGF and IL6, have been associated individually with a range of non-mitochondrial diseases, encompassing cancer, obesity, renal disease, diabetes, and liver disease, although many of them are characterized by an OXPHOS dysfunction." (PMID 32397676, 2020).
IL6 also shares sentences with these, for which no sentence is quoted: multiple myeloma (292 papers); chronic periodontitis (111); acute myocardial infarction (82); viral diseases (27); Parkinson’s (26); acute respiratory failure (20); hypertrophy (15); Alcohol (14); cardiac arrhythmia (14); leukoplakia (12); portal hypertension (12); concussion (10); Ventricular hypertrophy (10); autonomic dysfunction (9); polymyalgia rheumatica (9); dialysis (7); acute myocarditis (6); joint effusion (6); magnesium deficiency (6); prostate hyperplasia (6); Skeletal muscle atrophy (6); thrombophilia (6); adult respiratory distress syndrome (5); chronic prostatitis (5); corneal ulceration (5); erectile dysfunction (5); glomerulopathy (5); internal carotid artery stenosis (5); monocytopenia (5); oral submucous fibrosis (5).
A further 464 diseases each share a sentence with IL6 in 5 papers or fewer.